ASAH1 (N-acylsphingosine amidohydrolase 1)
Diseases named in the same sentence as ASAH1 in open-access papers (continued):
Sharing a sentence is not in itself a finding about the gene and the disease.
hydrops fetalis (1 paper, 2023). Hydrops fetalis is a severe and challenging fetal condition usually defined as the excessive accumulation of fetal fluid within the fetal extravascular compartments and body cavities that manifests as edema, pleural and pericardial effusion and ascites. "Here, we present a case of ASAH1‐associated disease presenting with severe hydrops fetalis." (PMID 37962265, 2023). "Herein, we demonstrate that the acceptor splice site variant (c.458‐2A>T) in intron 6 of ASAH1 can cause truncation or exon skipping, which is typically accompanied by loss‐of‐function subsequently leading to severe hydrops fetalis and early embryonic lethality." (PMID 37962265, 2023). "Our findings highlight the importance of ultrasonic manifestation and family history of fetal hydrops during ASAH1‐related disorders." (PMID 37962265, 2023). "We report a case of hydrops fetalis with a novel homozygous mutation in ASAH1 inherited from non‐consanguineous parents." (PMID 37962265, 2023).
Infertility (1 paper, 2023). "The first two published attempts at Asah1 knockout mouse model generation resulted in early embryonic lethality and infertility." (PMID 36830643, 2023).
invasive breast carcinoma (1 paper, 2020). A carcinoma that infiltrates the breast parenchyma. "However, high expression of ASAH1 was associated with improved prognosis in invasive breast cancer." (PMID 32236130, 2020).
metastatic melanoma (1 paper, 2024). A melanoma that has spread from its primary site to another anatomic site. "Moreover, the expression of ASAH1 in tumors from metastatic melanoma patients, combined from public cohorts and classified according to our 3 previously defined scores, is lower in the transitory and dedifferentiation states when compared to the differentiated state." (PMID 39136013, 2024).
Niemann-Pick disease, type C1 (1 paper, 2021). Type C Niemann-Pick disease associated with a mutation in the gene NPC1, encoding Niemann-Pick C1 protein. "Interestingly, recent study has demonstrated that ASAH1 overexpression increase GSH levels and reduce oxidative stress in fibroblasts derived from Niemann-Pick’s disease type C1." (PMID 34202192, 2021).
oral cancer (1 paper, 2023). "Therefore, the maintenance of diminished ASAH1 gene expression leading to the accumulation of intracellular ceramide in OSCC has emerged as a potential objective for oral cancer therapy." (PMID 37016912, 2023). "The maintenance of diminished acid ceramidase (ASAH1) gene expression leading to the accumulation of antiproliferative intracellular ceramides in oral squamous cell carcinoma (OSCC) has emerged as a prospective oral cancer therapeutic regimen." (PMID 37016912, 2023).
parasitemia (1 paper, 2022). "However, T cell-specific Ac ablation had no impact on the course of P. yoelii infection as Ac CD4cre KO (Asah1/Cd4cre/+) and Ac CD4cre WT (Asah1/Cd4+/+) mice showed similar spleen weights and parasitemia 7 and 14 days p.i.." (PMID 36094170, 2022). "However, upon P. yoelii infection, Ac Lyz2cre KO (Asah1/Lyz2cre/+) mice and Ac Lyz2cre WT (Asah1/Lyz2+/+) littermates did not significantly differ regarding parasitemia and spleen weight." (PMID 36094170, 2022).
proteinopathy (1 paper, 2023). "Of the four studied genes encoding ceramidase, the level of mRNA of acid ceramidase Asah1, localized in lysosomes, was the one increasing during the progression of FUS-mediated proteinopathy." (PMID 36836867, 2023).
thalassemia (1 paper, 2023). An inherited blood disorder characterized by a decreased synthesis of one of the polypeptide chains that form hemoglobin. "After excluding thalassemia carriers from the parents, we subjected the fetus and parents to CNV‐Seq and WES, respectively, and detected a novel splice site variant in ASAH1." (PMID 37962265, 2023).
type 1 diabetes (1 paper, 2020). "Singh and colleagues also reported that youths with type 1 diabetes excreted higher amounts of lumican, CD14, and various lysosomal proteins such as ASAH1, CTSD, and NAGA compared to their non-diabetic siblings." (PMID 32453760, 2020).
cancer (70 papers, 2010 to 2026). A tumor composed of atypical neoplastic, often pleomorphic cells that invade other tissues. "Among these ceramidases, acid ceramidase (AC), encoded by the gene ASAH1, is particularly significant due to its potential role in cancer progression and resistance to therapy." (PMID 41596686, 2026). "The ASAH1 gene, which encodes the enzyme acid ceramidase, has been implicated in cancer progression." (PMID 41012124, 2025). "ASAH1 expression is associated with tumor growth, progression, and poor response to therapy, highlighting its potential role as a target for cancer therapy." (PMID 38926346, 2024). "Currently, ASAH1 has been reported to be associated with drug resistance and is a therapeutic target for cancer." (PMID 36068514, 2022). "ASAH1 has been identified in cancer cells and is associated with radiotherapy/chemotherapy-resistant tumors, metastatic cell lines, and estrogen/progesterone/androgen receptor-positive cells." (PMID 32498325, 2020). "The results suggest that ASAH1 and its encoded AC protein are crucial to maintain cancer cell malignancy." (PMID 28785021, 2017). "ASAH1 inhibition or downregulation leads to loss of cancer cell viability, anchorage-independent growth and metastatic potential, and sensitizes to cell death induced with Fas ligand and radiotherapy." (PMID 24970218, 2014). "Given itscentral role in sphingolipid metabolism and potentialimpact on therapy response, further studies are neededto investigate ASAH1 expression and activity inrectal cancer patients to determine its associationwith tumour development and treatment outcomes." (PMID 40821650, 2025). "Indeed, higher expressions of ASAH1 detected in ER+ compared to ER- BCs was mainly associated with Luminal A cancers, which are known to have the better prognosis and positive outcomes of all BC subtypes, suggesting the high ASAH1 expression as a useful biomarker for the Luminal phenotype." (PMID 36768427, 2023). "Given ceramides’ diverse functions in regulating cell growth, differentiation, and apoptosis, targeting ASAH1 holds promise for cancer therapy." (PMID 38926346, 2024). "We initially analyzed sphingolipid profiles to identify differences between parental cancer cells and their polyploid derivatives in the absence and presence of the ASAH1 inhibitor LCL521." (PMID 34062962, 2021). "In an effort to exploit ASAH1 as a pharmacological target, several inhibitors have been developed for cancer therapeutics." (PMID 34102611, 2021). "It has been shown that ASAH1 promotes resistance of cancer cells to radiation therapy, and depletion of ASAH1 using RNAi improved the therapeutic response." (PMID 34102611, 2021). "It is important to mention, however, that there seems to be a dual function for ASAH1 by which it promotes cancer growth and progression." (PMID 33766731, 2021). "The ASAH1 mRNA expression in cancer cells can be increased by radiotherapy, thereby generating resistance." (PMID 32498325, 2020). "The elevated transcription of ASAH1 has been reported in a number of cancers, including GBM, and has been found to confer resistance to apoptosis." (PMID 31906280, 2020). "Recently, targeting ASAH1 for cancer treatment has been shown to enhance the efficacy of chemotherapy, which identifies ASAH1 as a therapeutic target." (PMID 31817238, 2019). "The most surprising and, possibly, most important finding of the present study is that cancer-initiating cell generation is virtually abolished in ASAH1-null cells." (PMID 28785021, 2017). "Recently, targeting ASAH1 for cancer treatments has generated significant interest, as reported by multiple studies, which identified ASAH1 as a therapeutic target." (PMID 29348854, 2017). "In search for ceramidase inhibitors, most efforts have been directed to Asah1 inhibition, because of their potential used as antiproliferative and cytostatic drugs for cancer chemotherapy." (PMID 20137073, 2010).
cancer (continued). "Asah1 is overexpressed in several cancer cell lines and cancer tissues, which appears to contribute to decreasing the levels of ceramide and increasing those of S1P." (PMID 20137073, 2010). "However, we previously detected ASAH1 in early endosomes in cancer cell lines, as isolated by Endo-IP using EEA1 (early endosomal antigen 1) as the affinity handle 24, suggesting its localization in less mature endolysosomal compartments." (PMID 41279717, 2025). "Previous studies have highlighted ASAH1’s significance in various cancers." (PMID 38926346, 2024). "ASAH1 elevation has been found in a variety of cancers, but the specific molecular mechanism of ASAH1 upregulation and the relationship between ASAH1 and ROS remain unclear." (PMID 38924190, 2024). "It seemed that the roles of ASAH1 in cell death in inflammation may be different from those in cancer." (PMID 36068514, 2022). "Others have suggested that ASAH1 may contribute to drug resistance of tumors, perhaps by promoting and maintaining survival of cancer stem cells." (PMID 29348854, 2017). "The secreted ASAH1 may, in principle, diffuse into nearby cancer cells or even normal cells, enabling them to become more resistant to radio- and chemotherapy, promoting cell growth and angiogenesis." (PMID 29348854, 2017). "Therefore, the mechanism through which ASAH1 inhibition decreases migration may be specific to certain cancer types." (PMID 35741006, 2022). "In addition, ASAH1 overexpression has been reported in various human cancers." (PMID 34822527, 2021). "The ASAH1 enzyme is overexpressed in multiple human cancers and may promote cancer progression." (PMID 32236130, 2020). "Thus, several ASAH1 inhibitors have been developed for use in cancer therapies." (PMID 31817238, 2019). "Thus, several ASAH1 inhibitors are being developed for use in different cancer treatments." (PMID 29348854, 2017). "Many cancer-related genes, such as ZMYND8, ASAH1, and SELENBP1, were found mis-spliced following the degradation of RBM39." (PMID 40223119, 2025). "The results for mRNA expression levels of ASAH-1 and ACER3 in CRC tissue were significantly higher in cancer tissues than in normal paired tissue, respectively (p = 0.0088, 0.0001)." (PMID 37758931, 2023). "In this study, we compared transcriptomes of parental cancer cells and PGCC in the absence or presence of the ASAH1 inhibitor LCL521." (PMID 35624221, 2022). "As expected, treatment with LCL521 decreased the ASAH1 product sphingosine and its phosphorylated downstream metabolite S1P in both parental PPC1 cancer cells as well as the stress-induced PGCC." (PMID 34062962, 2021). "We have previously shown that ASAH1 expression increases in PGCC and its activity is critical for PGCC progeny formation across cell lines from different types of cancer." (PMID 34062962, 2021). "Additionally, several genes exhibited significant expression differences across cancers, such as SCD and ASAH1, downregulated in LUAD but upregulated in other cancers." (PMID 39393173, 2024). "The goal of this study was to understand differences in sphingolipid metabolism between non-polyploid and polyploid cancer cells to gain an understanding of the ASAH1-dependence in the PGCC population." (PMID 34062962, 2021). "We found that tamoxifen provided a significant increase in survival for the second (nonbreast) cancer, which suggests the possibility that tamoxifen contributed to inhibition of ASAH1." (PMID 32135040, 2020). "In cancers that are not estrogen‐fueled, high ASAH1 levels likely reflect resilience due to stress adaptation." (PMID 32135040, 2020). "Compared to parental cancer cells, PGCC-independent of ASAH1 inhibition- had lower expression of INSIG1 protein, more efficiently effluxed cholesterol, and expressed high levels of SR-B1." (PMID 35624221, 2022). "Our results also showed that CD133+ GSCs express a very high level of ASAH1 compared to CD133- GSCs and non-stem cancer cells, such as U87MG cells." (PMID 29348854, 2017).
tumor (56 papers, 2009 to 2025). "BothS1P and C1P have been implicated in tumour progression,highlighting the importance of ASAH1 inregulating their availability." (PMID 40821650, 2025). "Recent studies have shown that ASAH1 is associated with the development of drug resistance in tumour cells." (PMID 38924190, 2024). "However, in sharp contrast to the physiological status, tumor lung tissues showed that higher levels of STING were associated to higher levels of ASAH1." (PMID 37176007, 2023). "Several glycoproteins associated with the lysosomal pathway, including LAMP1, ASAH1, ATP6AP1, and HEXA, exhibited significantly increased levels of specific glycoforms bearing high-mannose glycans in tumor tissue." (PMID 41061966, 2025). "Two approaches indicated a significant reduction in ASAH1 expression in tumor tissue (p=0.004 and p<0.001, respectively)." (PMID 41313810, 2025). "We also observed similar tumor-suppressive effect on growth of TNBC cells with another ASAH1 inhibitor, Ceranib-2." (PMID 38926346, 2024). "ASAH1 converts ceramide to sphingosine and free fatty acids, thereby creating a favorable environment for tumor growth." (PMID 38926346, 2024). "Collectively, these results demonstrated that genetic inhibition of ASAH1 can block the tumor growth of TNBC and metastasis." (PMID 38926346, 2024). "Consistent with the results obtained in the cell culture experiments, ASAH1 knockdown inhibited the subcutaneous TNBC tumor growth in vivo." (PMID 38926346, 2024). "In this study, we found that in tumor cells the activation of STING by means of cGAMP resulted in an increased activation of ASAH1 responsible for S1P synthesis, as already reported." (PMID 37176007, 2023). "Although there were similarities in the two pathways during physiological and pathological conditions, it has to be noted that the expression of STING when the tumor was present was positively correlated to the expression of ASAH1." (PMID 37176007, 2023). "One explanation for the differences between our in silico and in vitro analyses is the presence of ASAH1 in the tumor microenvironment." (PMID 38086808, 2023). "Collectively, these data support the notion that ASAH1 contributes to TSC tumor progression and dissemination to the lungs in LAM." (PMID 36927688, 2023). "We postulate that combinatorial suppression of mTORC1 and ASAH1 will inhibit tumor growth beyond what is achieved with mTORi alone." (PMID 36927688, 2023). "We next assessed the possible benefit of the ASAH1 inhibitor 17a in a xenograft tumor model in which Tsc2-null ELT3 luciferase-expressing cells were implanted subcutaneously into immunodeficient NOD/SCID-γ–null (NSG) mice." (PMID 36927688, 2023). "Our studies show that suppression of ASAH1 using 17a and ASAH1 shRNA attenuates xenograft tumor progression and growth of renal cystadenomas in Tsc2+/– A/J mice." (PMID 36927688, 2023). "ASAH1 depletion significantly delayed the onset of tumors and decreased tumor progression by 4.2-fold, compared with pLKO.1 control–transduced cells." (PMID 36927688, 2023). "Of the ceramidases which hydrolyze ceramides, acid ceramidase (ASAH1) is highly expressed in GBM samples compared to non-tumor brain." (PMID 35741006, 2022). "ASAH1 levels were significantly higher in GBM tissue compared to non-tumor brain in Gravandeel and TCGA GBM Agilent-4502A and similarly trended higher in TCGA GBM HG-U133A (p = 0.0516)." (PMID 35741006, 2022). "To understand the expression pattern of ASAH1 in GBM as compared to non-tumor brain, we evaluated ASAH1 gene expression in three different publicaly available patient mRNA datasets." (PMID 35741006, 2022). "For instance, ASAH1 plays a role in the ceramide signalling pathway and other processes such as inducing apoptosis for tumour cell death." (PMID 32883995, 2020). "Further investigation is needed to determine if a similar protective benefit against tumor progression can be seen in GBM patients that developed auto anti-ASAH1 antibodies through active immunization." (PMID 29642535, 2018).
tumor (continued). "Of the four, the CHLA200 line, which was generated from a recurrent tumor at autopsy believed to be resisted to both chemo- and radiotherapy, was noted to have the highest expression level of ASAH1, many fold higher." (PMID 28445970, 2017). "Investigators reported that over-expressed ASAH1 in cells resulted in larger tumor volumes that are more resistant to chemotherapy, and when ASAH1 is suppressed, cells became more sensitive to chemotherapy." (PMID 29348854, 2017). "Quantification of the IHC staining of ASAH1 was carried out by Allred scoring system based on the proportion of positively stained tumor cells (proportion score, PS) and the estimated staining intensity (intensity score, IS)." (PMID 29348854, 2017). "Additionally, ASAH1 secretion into interstitial tissues facilitates tumor progression by modifying the surrounding microenvironment." (PMID 40628732, 2025). "We then tested the effects of ASAH1 knockdown on TNBC tumor growth in vivo." (PMID 38926346, 2024). "ASAH1 plays an important role in regulating ceramide metabolism and tumor pathogenesis." (PMID 38589907, 2024). "We next investigated whether trametinib and the ASAH1 inhibitor carmofur can be combined to achieve even stronger TNBC tumor growth inhibition." (PMID 38926346, 2024). "Furthermore, DUSP5 overexpression in NS shRNA-expressing cells inhibited TNBC tumor growth, whereas DUSP5 knockdown in the ASAH1 shRNA expressing partially restored ASAH1 inhibition induced tumor growth inhibition." (PMID 38926346, 2024). "GSEA analysis showed that tissues of ASAH1+ patients were mainly characterized by metabolic pathways (fatty acid metabolism, bile acid metabolism, heme metabolism, adipogenesis, cholesterol homeostasis) compared to ASAH1− patients, as observed in non-tumor tissues." (PMID 37176007, 2023). "Similarly to what was performed on normal lung tissues, we analyzed the public TCGA_LUAD_2016 database to evaluate both STING and ASAH1 mRNA levels in tumor tissues." (PMID 37176007, 2023). "In NSCLC-derived cells, resistance to ChoKαIs is overcome by overexpression of acid ceramidase (ASAH1) in keeping with the known mechanism of action of ChoKαIs of inducing increased levels of ceramides and allows the identification of tumours resistant to treatment with ChoKαIs." (PMID 34070409, 2021). "Furthermore, both bioinformatics analysis and experimental results showed that TAOK2 was down-regulated and ASAH1 was up-regulated in male tumor tissue and female tumor tissue in LUAD." (PMID 32236130, 2020). "Alternatively, employing immunotherapy or a tumor vaccine against secreted ASAH1 may also be an important strategy to be considered in future studies." (PMID 29642535, 2018). "Therefore, there may be positive feedback in the AKT/ASAH1 regulatory network that accelerates tumour progression." (PMID 38924190, 2024). "Therefore, MCL stabilized the antioxidant regulatory protein NRF2 by directly binding to KEAP1 and promoting its nuclear translocation, thereby attenuating oxidative stress in MCF7TAMR cells, and ultimately suppressing tumour proliferation through the ROS/pAKT/ASAH1 pathway." (PMID 38924190, 2024). "Therefore, inhibiting ASAH1 pharmacologically may have additional benefits within the tumor microenvironment such as decreasing macrophage recruitment." (PMID 38086808, 2023). "Genes such as ACER1, ASAH1 and SMPD1 exhibit significant differences in expression between tumour and normal tissues." (PMID 40159631, 2025). "In our study, we identified four key genes (ALDH1A1, ASAH1, CDT1, and CDC45) that affect tumor cell stemness and lymph node metastasis." (PMID 38589907, 2024). "Collectively, these results demonstrated that ASAH1 is necessary for TNBC development and that its pharmacological inhibition leads to the impairment in TNBC tumor growth and metastasis." (PMID 38926346, 2024).